RYR2 (ryanodine receptor 2)
Diseases named in the same sentence as RYR2 in open-access papers (continued):
Sharing a sentence is not in itself a finding about the gene and the disease.
catecholaminergic polymorphic ventricular tachycardia (continued). "Lastly, catecholaminergic polymorphic ventricular tachycardia (CPVT), a stress-induced ventricular rhythm disease caused by mutations in the cardiac ryanodine receptor isoform 2 (RyR2) gene, has also been shown in CMs derived from iPSCs isolated from patients with CPVT (CPVT1-CMs)." (PMID 27110250, 2016). "Variations in genes implicated in cardiac calcium signaling have been shown to cause a number of arrhythmia syndromes, including long-QT syndrome 4 (ANK2) and 8 (CACNA1C), Brugada syndrome (CACNA1C) and catecholaminergic polymorphic ventricular tachycardia (RyR2)." (PMID 27857207, 2016). "In particular, RYR2 has previously been reported as gene associated with several arrhythmic diseases, including LQTS, catecholaminergic polymorphic ventricular tachycardia (CPVT), arrhythmogenic right ventricular dysplasia type 2 and sudden infant death syndrome." (PMID 26132555, 2015). "The disease mechanisms have been attributed to dysregulation of RyR2, for Catecholaminergic Polymorphic Ventricular Tachycardia (CPVT) and/or CaV1.2, for Long-QT Syndrome (LQTS)." (PMID 37663247, 2023). "The antiarrhythmic actions of flecainide on RyR2 channels have also been demonstrated in a cardiac calsequestrin knockout catecholaminergic polymorphic ventricular tachycardia (CPVT) mouse model." (PMID 35456912, 2022). "Flecainide blocks ryanodine receptor type 2 (RyR2) channels in the open state, suppresses arrhythmogenic Ca2+ waves and prevents catecholaminergic polymorphic ventricular tachycardia (CPVT) in mice and humans." (PMID 26121139, 2015). "Mice with gain-of-function RyR2 mutations causing catecholaminergic polymorphic ventricular tachycardia (CPVT), and mice lacking the RyR2-stabilizing subunit FKBP12.6, develop Ca2+-handling abnormalities including increased SR Ca2+-leak and spontaneous SR Ca2+-release events (i.e., sparks, waves)." (PMID 24624086, 2014). "On the other hand, other groups have suggested that PKA phosphorylation of RyR2 is so essential to intracellular Ca2+ homeostasis that derangement of this process may be the basis for heart failure (HF) and catecholaminergic polymorphic ventricular tachycardia (CPVT) episodes." (PMID 21798098, 2011). "Here, we profile respiratory safety and cellular uptake of an inhaled siRNA targeting the cardiac RyR2 gene, which is responsible for catecholaminergic polymorphic ventricular tachycardia (CPVT), delivered via inhalation with calcium phosphate nanoparticles (CaP NPs)." (PMID 41984094, 2026). "In failing hearts or catecholaminergic polymorphic ventricular tachycardia (CPVT), RyR2 sensitivity to Mg2+ inhibition is decreased, promoting arrhythmogenic Ca2+ release." (PMID 40862759, 2025). "For example, mutations leading to spontaneous Ca2+ release from RYR2 (ryanodine receptor 2; OMIM: 180902) sarcoplasmic reticulum (SR) Ca2+ release channels result in catecholaminergic polymorphic ventricular tachycardia (CPVT) and atrial fibrillation (AF)." (PMID 40722594, 2025). "Catecholaminergic polymorphic ventricular tachycardia (CPVT) is an inherited arrhythmia syndrome characterized by defective cardiac ryanodine receptor (RyR2) calcium release during times of adrenergic stimulation, resulting in bidirectional or polymorphic ventricular tachycardia." (PMID 38024821, 2023). "For instance, flecainide prevents arrhythmias in a mouse model of Catecholaminergic Polymorphic Ventricular Tachycardia (CPVT) by inhibiting cardiac RYR2–mediated Ca2+ release and is now considered a valid therapeutic approach in CPVT patients non-responsive to betablockade alone." (PMID 36371290, 2022). "Some studies have shown that carvedilol suppresses RyR2-mediated calcium waves and prevents calcium release-induced triggered ventricular arrhythmias in patients with catecholaminergic polymorphic ventricular tachycardia (CPVT) or heart failure (HF)." (PMID 35885069, 2022).
catecholaminergic polymorphic ventricular tachycardia (continued). "The RYR2 mutations have been established in the etiology of arrhythmogenic right ventricular dysplasia 2 (ARVD2) and catecholaminergic polymorphic ventricular tachycardia (CPVT)." (PMID 33897349, 2021). "An interesting genetic overlap has been described between ACM and catecholaminergic polymorphic ventricular tachycardia (CPVT) caused by a mutation in RYR2; however, the role of RYR2 in ACM must still be clarified because of the high background rate of rare missense RYR2 variants." (PMID 32878278, 2020). "Catecholaminergic polymorphic ventricular tachycardia (CPVT) is a stress-induced ventricular arrhythmia associated with cytoplasmic calcium leakage due to mutations in calsequestrin 2 (CASQ2), ryanodine receptor (RyR2), triadin, or calmodulin." (PMID 33329039, 2020). "For example, reduced RyR2 cluster sizes and fragmented JSR morphology have been observed in mouse models of catecholaminergic polymorphic ventricular tachycardia." (PMID 26545234, 2015). "A large genomic deletion in human cardiac ryanodine receptor (RYR2) gene has been detected in a number of unrelated families with various clinical phenotypes, including catecholaminergic polymorphic ventricular tachycardia (CPVT)." (PMID 24743769, 2014). "Notably, the panel refuted RYR2 as an ARVC gene, finding P/LP variants in RYR2 typically cause catecholaminergic polymorphic ventricular tachycardia (CPVT) not ARVC." (PMID 33831308, 2021). "Flecainide, which has demonstrated efficacy in catecholaminergic polymorphic ventricular tachycardia (CPVT) and ARVC, is thought to limit the outflow of calcium through the RyR2 channel." (PMID 37189831, 2023). "In our previous works, we have found similar changes (fragmentation of CRUs), i.e., reduction in size of RYR2 clusters, in mouse models lacking calsequestrin-2 (CASQ2) and carrying human mutations in CASQ2 linked to catecholaminergic polymorphic ventricular tachycardia." (PMID 34445071, 2021). "In addition, hiPSC-derived cardiomyocytes carrying mutations to ryanodine receptors (RyR2) calcium/calmodulin-dependent protein kinase II (CaMKII) and calsequestrin (CLSQ) displayed calcium oversensitization, the hallmark of catecholaminergic polymorphic ventricular tachycardia (CPVT)." (PMID 28044126, 2016). "RYR2, despite previously reported in association with ACM, was disqualified as an ACM-causative gene due to contradictory evidence and because it proved to be associated to catecholaminergic polymorphic ventricular tachycardia (CPVT) rather than ACM." (PMID 35448074, 2022). "Other conditions include Brugada syndrome, where over 350 pathogenic mutations were found in the SCN5A (18–30%) and a dozen other genes (though 65% of cases do not have a genetic origin), and catecholaminergic polymorphic ventricular tachycardia (CPVT), affected by RyR2." (PMID 33540853, 2021). "Furthermore, the gene RYR2 was screened in 36 selected LQTS genotype-negative patients to detect cases with the clinically overlapping disease catecholaminergic polymorphic ventricular tachycardia (CPVT)." (PMID 23098067, 2012). "Notably, RYR2 was disqualified as an ARVC gene with the investigators reporting that patients and model systems in the literature had catecholaminergic polymorphic ventricular tachycardia (CPVT), not ARVC." (PMID 34926342, 2021).
Arrhythmia (193 papers, 2009 to 2026). Any cardiac rhythm other than the normal sinus rhythm. "Dysregulation of RyR2 function is a key pathogenic factor in various cardiac diseases, notably arrhythmias and heart failure." (PMID 42222672, 2026). "RYR2 is an important large calcium channel that is predominantly expressed in the heart with mutations linked to myopathies and arrhythmias." (PMID 40200715, 2025). "CPVT results from a mutation in the RyR2 gene and is clinically characterized by episodes of syncope, arrhythmias, or sudden cardiac arrest." (PMID 40575238, 2025). "On the other hand, RYR2 loss-of-function variants have also been associated with arrhythmias and RYR1 loss-of-function has been reported in skeletal myopathies." (PMID 40060969, 2025). "Defective RYR2 gating and the associated aberrant Ca2+ release from the SR during diastole trigger arrhythmia initiation in PKP2 cKO mice." (PMID 41468454, 2025). "The RyR2-R420Q CPVT mouse model has previously been shown to develop similar stress-induced arrhythmias in vivo as patients with the same mutation, such as bidirectional VT, sinus bradycardia, and junctional escape." (PMID 40612651, 2025). "The diagnostic criteria for LQTS associated with RYR2 variants, especially when considering the complexity of RYR2-related arrhythmias, involve a combination of genetic testing and clinical assessment." (PMID 40910028, 2025). "This pathogenic mechanism is further highlighted by studies in PDE4D-deficient mice, where PKA hyperphosphorylation of RyR2 leads to increased susceptibility to exercise-induced arrhythmias and late-onset dilated cardiomyopathy." (PMID 40136709, 2025). "The oxidant environment prevailing in the failing cardiomyocyte seems to promote both phosphorylation and oxidation of RyR263 and calmodulin, which translates into RyR2 leakiness and consequent contractile impairment and increased susceptibility to arrhythmia." (PMID 40562493, 2025). "Hyperphosphorylation of RyR2 has been implicated in the pathogenesis of various cardiac dysfunctions, including myocardial systolic and diastolic dysfunction, arrhythmias, and heart failure." (PMID 40599813, 2025). "In a separate study, augmentation of CASQ2 expression in a model of RYR2-mediated CPVT1 significantly mitigated arrhythmia susceptibility." (PMID 40843724, 2025). "Exercise or stress-induced arrhythmias can be observed in the presence of RYR2 variants that often experience arrhythmias that are triggered by physical or emotional stress, not typically associated with the classic prolonged QT intervals seen on an ECG." (PMID 40910028, 2025). "RyR2 plays a major role in cardiac excitation–contraction coupling, and mutations in this isoform can give rise to cardiac arrhythmias." (PMID 40003308, 2025). "Collectively, our data suggest that PDE4B can physically associate with and predominantly regulates cAMP levels in the RyR2 microdomain, as well as arrhythmia susceptibility upon prolonged catecholamine exposure." (PMID 38534320, 2024). "They reported that iPSC-CMs derived from dermal fibroblasts of patient with inherited CPVT1 (caused by mutation in the RYR2 p.F2483I), exhibited arrhythmias and delayed afterdepolarizations (DADs) after catecholaminergic stimulation." (PMID 39328831, 2024). "Mutations in the ryanodine receptor (RyR2) gene have been linked to arrhythmia and possibly sudden cardiac death (SCD) during acute emotional stress, physical activities, or catecholamine perfusion." (PMID 39590361, 2024). "The combined effect of the mutation in RyR2 and catecholaminergic stimulation is the triggering of an arrhythmia." (PMID 39590361, 2024). "Over 200 point mutations in the ryanodine receptor (RyR2) of the cardiac sarcoplasmic reticulum (SR) are known to be associated with cardiac arrhythmia." (PMID 39768143, 2024).
Arrhythmia (continued). "The primed state is such that RyR2 in a failing heart would be readily and inappropriately activated by stress conditions, resulting in uncontrolled diastolic SR Ca2+ leak and cardiac arrhythmias, which are the cause of death of most patients with HF." (PMID 39278969, 2024). "mutations in ryanodine receptor 2 (RYR2) are commonly thought to be strongly associated with lethal arrhythmias and heart failure." (PMID 36969232, 2023). "Specifically, a major cause of triggered arrhythmia is spontaneous RyR2-mediated SR Ca2 + release, driving inward Na + current via the NCX, leading to EAD and in particular DAD formation, which are important cellular arrhythmia mechanisms in AF, VT, and SCD23." (PMID 37775650, 2023). "Most of the CPVT1-associated RyR2 mutations cause enhanced Ca2+ release with delayed afterdepolarizations (DADs) and arrhythmias and are considered as gain-of-function mutations." (PMID 37894987, 2023). "We investigated RyR2 mRNA expression by RT-PCR and found that the RyR2 mRNA level was closely related to the occurrence of arrhythmia caused by BaCl2." (PMID 37598173, 2023). "In summary, this study revealed that FSM mitigated BaCl2 induced cardiac damage caused by arrhythmia by suppressing RyR2 expressions, decreasing adrenaline and cAMP through the adrenergic signalling pathway." (PMID 37598173, 2023). "Working with Robert (“Rocky”) Kass and Jon Lederer on understanding the molecular basis for cardiac arrhythmias led to my interest in how sympathetic nervous system activation linked to stress affected RyR2 channels in the heart." (PMID 36647824, 2023). "Arrhythmias associated with CPVT4 typically have altered RYR2 function but can also occur by diminished function of other channels which influence the concentration of ions in the cardiac myocyte." (PMID 36671457, 2022). "In conclusion, we presented an in-depth characterization of the recognition between a common CaM-binding region in RyR1 and RyR2 and two arrhythmia-associated CaM variants in their Ca2+-bound states." (PMID 36685279, 2022). "The present studies have shown that the inhibition of NOS1 decreased RYR2 activity because of reducing Ca2+ sparks and shortened action potential causing arrhythmia susceptibility." (PMID 35924220, 2022). "Abnormal interaction between CaM and RyR2 due to mutations in the CaMBD of RyR2 or in CaM itself can cause severe cardiac complications, including cardiac hypertrophy, heart failure and arrhythmias, such as CPVT." (PMID 34888671, 2022). "Traditionally, RYR2 mutations were commonly considered to be associated with heart failure and arrhythmias." (PMID 36578478, 2022). "As variants in RYR2 are associated with adrenergically mediated arrhythmias, we tested the effect of adrenergic stimulation on the hiPSC‐CMs using isoproterenol." (PMID 35439358, 2022). "This leads to an increase in SR Ca2+ leak and of [Ca2+]i due to long-lasting open states of RyR2 that cause arrhythmia and dysfunction in heart failure." (PMID 35047109, 2022). "The studies showed that the inhibition of NOS1 decreased RYR2 activity because of reducing Ca2+ sparks and shortened action potential causing arrhythmia susceptibility." (PMID 35924220, 2022). "Here, we investigated how arrhythmia-associated mutations in CaM localized at the C-terminal lobe alter the molecular recognition with Ryanodine receptor 2 (RyR2), specifically expressed in cardiomyocytes." (PMID 35133504, 2022). "While the mechanisms of RyR2-linked arrhythmias are well characterized, little is known about the mechanism underlying RyR2-associated intellectual disability." (PMID 35233070, 2022). "RYR2 was traditionally considered to be associated with heart failure and arrhythmias, but recently, some studies have identified complex communication mechanisms between RYR2 and immune cells and immune-related molecules." (PMID 36578478, 2022).
Arrhythmia (continued). "As it was shown in the HFD-induced DM mice model, increased mitochondrial ROS is accompanied with elevated levels of cardiac IL-1β (interleukin), increased oxidation of SR Ca2+ channel RyR2, and subsequent Ca2+ leakage through it and risk of arrhythmia." (PMID 35887211, 2022). "In support, increased RyR2 function as a result of RyR2 mutations can lead to lethal cardiac arrhythmias, such as CPVT2, ID and cognitive deficits." (PMID 35233070, 2022). "Under conditions of increased ER stress such as cardiac hypertrophy, upregulation of ERO1α removes ERp44 from the RyR2 channel complex, contributing to spontaneous Ca2+ release from the SR and increased risk for Ca2+-dependent arrhythmias." (PMID 36425292, 2022). "Mutations Q3970E/K in RyR1 are implicated in central core disease and equivalent RyR2 mutations in cardiac arrhythmia, which highlights the important Ca2+ sensing role for this residue." (PMID 35257661, 2022). "Mutations in thecardiac ryanodine receptor type 2 (RyR2) havebeen linked to fatal cardiac arrhythmias such as catecholaminergicpolymorphic ventricular tachycardia (CPVT)." (PMID 36384028, 2022). "Mutations in RyR2 generally lead to the Ca2+ leak that is associated with heart failure and arrhythmias." (PMID 35677449, 2022). "Ryanodine receptor 2 constituting the major intracellular Ca2+ release channel in the cardiac sarcoplasmic reticulum has been linked to cardiac arrhythmias and heart failure." (PMID 35048506, 2022). "RyR2 mutations have largely been associated with CPVT characterized by stress-induced arrhythmias, and associated with an enhanced Ca2+ release under adrenergic stimulation." (PMID 33664309, 2021). "We have previously shown that exercise training can prevent β‐adrenoceptor stimulation‐induced arrhythmias in mice with the CPVT1‐causative mutation RyR2‐R2474S (RyR2‐RS)." (PMID 34558218, 2021). "The N-terminus domain of RyR2, one of the three arrhythmia-associated mutation hot-spots, is an important structural and functional regulatory element involved in both activation and termination of SR Ca2+ release." (PMID 32077934, 2021). "In this model, an increase in RyR2 phosphorylation by CaMKII leads to higher susceptibly to in vivo arrhythmia and spontaneous SR Ca2+ release although RyR2 expression was decreased." (PMID 34690808, 2021). "Cardiac myocytes from mice that were fed a fructose-rich diet exhibited arrhythmias caused by the exacerbation of Ca2+/calmodulin-protein kinase (CaMKII) activity, phosphorylation of ryanodine receptor 2 (RyR2), and sarcoplasmic reticular Ca2+ leakage." (PMID 34201938, 2021). "Stimulation of both 5-HT and adenosine A2A receptors has been linked to arrhythmias by increasing cAMP and its RyR2-dependent activation." (PMID 34831263, 2021). "More attention should be paid to epilepsy patients with RYR2 mutations, which were associated with arrhythmia and sudden unexpected death in previous reports." (PMID 33897349, 2021). "The small differences in Ca2+ wave frequency between CPVT1 and WT cardiomyocytes observed here do not seem to reflect the large effects of the CPVT1 mutation on arrhythmias in vivo (e.g., 50%–75% VT incidence in RyR2‐RS groups compared to 0% in WT)." (PMID 34558218, 2021). "This mutation induced a Ca2+ leak through the RyR2, that was responsible for both arrhythmia and epilepsy episodes under stress." (PMID 34725342, 2021). "The phenotypes for the mutant patient-derived hiPSC-CMs is perhaps the best evidence yet for a causal link for a RyR2 variant and inherited cardiac arrhythmias." (PMID 34725342, 2021). "RYR2 gain-of-function variants cause catecholaminergic polymorphic ventricular tachycardia 1, producing lethal cardiac arrhythmias." (PMID 34930847, 2021). "CaM protein abnormality affects the release of Ca2+ from RyR2, which in turn causes abnormal Ca2+ concentration in cardiomyocytes and leads to arrhythmias." (PMID 34483927, 2021).